CALR (calreticulin)
Diseases named in the same sentence as CALR in open-access papers (continued):
Sharing a sentence is not in itself a finding about the gene and the disease.
cancer (continued). "Of note, non-immunogenic cytotoxic treatment of cancer cells was converted to immunogenic by co-treatment with recombinant calreticulin, highlighting the pivotal role of calreticulin in ICD." (PMID 25688334, 2015). "Like calreticulin, BiP/GRP78 also influences the way cancer cells interact with the immune system." (PMID 25386408, 2014). "Exogenous calreticulin also augmented CTL-mediated lysis of non-irradiated carcinoma targets relative to targets plus control protein (P < 0.0001)." (PMID 24480782, 2014). "However, in the presence of exogenous calreticulin, the level of CTL lysis of MDA-MB-231 carcinoma cells exposed to radiation increased further relative to irradiated targets plus control protein (P < 0.0001)." (PMID 24480782, 2014). "However, in the presence of calreticulin-blocking peptide, the radiation-induced increase in CTL lysis of MDA-MB-231 carcinoma cells was significantly reduced (P < 0.0001)." (PMID 24480782, 2014). "These three proteins (HSP gp96, PDI A3 and calreticulin) are involved in protein folding and consequently a subset (HSP gp96 and calreticulin) may play a role in anti-cancer immunogenicity." (PMID 24281099, 2010). "However, this interesting finding suggests that through calreticulin expression induction, HSV-1 infection may facilitate cancer cell phagocytosis by macrophages." (PMID 39196415, 2024). "The lack of effect to therapeutic cancer vaccination against mutant CALR could be explained by the highly immunosuppressive TME in MPN." (PMID 37662956, 2023). "In our work, we showed the exposure of calreticulin in a subpopulation of ferroptotic cells shortly before their rupture, as well as ATP, HMGB1, CXCL1, TNF and IFN-β release in the course of a drug- and genetically induced models of ferroptosis in cancer cells." (PMID 35760796, 2022). "Interestingly, the treatment of cancer cells with TRAIL, that induce the assembly of DISC (death-inducing signaling complex) and the proteolytical processing of Caspase 8, have reported to induce the exposure of calreticulin and immunogenic cell death." (PMID 33584695, 2020). "Macrophage-mediated programmed cell removal (PrCR) is based on Calreticulin (CRT), an “eat-me signal” on the surface of cancer cells, which interacts with LDL-receptor-related protein (LRP) on the macrophages and recruits macrophages to phagocytize cancer cells." (PMID 31528120, 2019). "In summary, these data indicate that ATCs express the dominant pro-phagocytic molecule calreticulin, as well as the “don't eat me” signal CD47 and the immune checkpoint molecules PD-1 and PD-L1, all of which are currently targeted therapeutically in other types of cancer." (PMID 30938231, 2019). "Unlike other cancer therapies, these anticancer therapies are known to induce immunogenic cancer cell death characterized by the release of tumor antigens and high levels of immune stimulators (DAMPs, adenosine triphosphate and cell-surface calreticulin)." (PMID 29472928, 2018). "We hypothesize that enhancing these already existing anti-regulatory T-cell responses through therapeutic cancer vaccination with arginase-I and PD-L1 derived epitopes can boost the neo-antigen specific immune response induced by vaccination with JAK2/CALR-mutant epitopes." (PMID 30327655, 2018). "Similarly, hypericin treated cancer cells actively exposed calreticulin, with no detectable levels of HSP90, calnexin, or BiP." (PMID 25688334, 2015). "In addition to calreticulin exposure, late apoptotic or necrotic release of HMGB-1 from dying cells, and subsequent binding to TLR-4 on dendritic cells was necessary to obtain optimal antigen presentation of chemotherapy or radiotherapy treated cancer cells." (PMID 25688334, 2015). "Therefore, the interplay between CD47 and CALR underscores their integral roles in modulating immune responses and presents promising avenues for therapeutic strategies, which should be oriented to selectively upregulate CALR and quench CD47 signaling on cancer cells." (PMID 39767726, 2024).
cancer (continued). "In addition, PrRT increased translocation of calreticulin in both cancer stem-cell- and non-stem-cell-like populations, potentially facilitating the immune attack on cancer stem cells, which are regarded as being more radioresistant; however, this potential was not tested." (PMID 33806808, 2021). "Indeed, although calreticulin-dependent ICD has been described for various cytotoxic agents in pre-clinical settings these typically have not translated into reports on effective anti-cancer immunity upon treatment of patients." (PMID 25688334, 2015). "Some of the transcriptomic alterations corresponded to typically altered genes and processes in cancer and Ph-negative MPN patients that are known to be triggered by mutant calreticulin without the intervention of JAK2/MPL." (PMID 36611979, 2023). "In fact, BoxA does induce the release of calreticulin and HMGB1; remarkably, though, BoxA does not induce cell death, which by itself excludes ICD as a possible mechanism of anti-cancer immunity." (PMID 34561422, 2021). "DAMPs released during ICD comprise chaperones of endoplasmic reticulum (ER) such as heat-shock proteins (HSPs) and calreticulin (CALR), type I interferons (I-IFNs), non-histone chromatin-binding protein HMGB1, ATP, annexin A1 (ANXA1), and cancer cell-derived nucleic acids." (PMID 35488303, 2022).
infection (92 papers, 2007 to 2026). The state of being infected such as from the introduction of a foreign agent such as serum, vaccine, antigenic substance or organism. "In this study, intranasal administration of recombinant calreticulin effectively accelerated the clearance of Pasteurella multocida in lambs and significantly alleviated respiratory tissue pathology caused by the infection." (PMID 40723838, 2025). "In this study, genes encoding calreticulin and EF-hand-containing proteins were upregulated by SA treatment or Cmm infection." (PMID 38434116, 2023). "Contig873_2, encoding a “Calreticulin” protein was induced after infection in P665 vs. Messire, and was also more expressed in the resistant bulk vs. susceptible bulk." (PMID 36307494, 2022). "Taken together, these results suggest that there is an association between infection of Salmonella Choleraesuis with active FimH and surface calreticulin presence and organization." (PMID 28770174, 2017). "Taking these two models into account, we found that the expression level of calreticulin correlates with the level of adhered SCΔfimH/C, which indicates that the receptor is involved in mediating infection specifically for this variant of FimH." (PMID 28770174, 2017). "This study confirmed that wild type B. ovis escapes from LAMP1+ compartment at early time points post infection, whereas the B. ovis vacuole acquires calreticulin marker, which is associated with intracellular multiplication at later time points." (PMID 26366863, 2015). "We used the Mi-CRT gene (AF402771.1) that encodes a calreticulin secreted in plants during infection and involved in the success of infection." (PMID 24704976, 2012). "However, intranasal calreticulin treatment significantly alleviated the pathological damage caused by the infection." (PMID 40723838, 2025). "Previous studies have shown that in various aquatic animals, the expression levels of calreticulin are significantly upregulated following infection by multiple pathogenic bacteria, suggesting a crucial role for calreticulin in pathogen recognition and clearance." (PMID 40723838, 2025). "EmCRT is a calreticulin secreted by Echinococcus multilocularis during its infection in host, playing an important role in evading host immune attack as a survival strategy." (PMID 42075754, 2026). "At 6 h post-infection, lambs were treated with calreticulin via intranasal administration to evaluate its effect on in vivo clearance of Pasteurella multocida." (PMID 40723838, 2025). "A significant increase in cell surface expression of calreticulin was observed at 48 h post infection with MV-s-NAP in all four cell lines by flow cytometry analysis." (PMID 41235176, 2025). "Accordingly, we established an intranasal infection model using Pasteurella multocida to assess the protective role of calreticulin against respiratory bacterial challenge." (PMID 40723838, 2025). "Following infection, calreticulin expression was markedly upregulated in the nasal mucosa, trachea, and lung tissues." (PMID 40723838, 2025). "Immunohistochemical staining revealed markedly increased calreticulin expression in these respiratory regions following infection." (PMID 40723838, 2025). "Post LOAd infection, all cells became positive for calreticulin but only three at significantly increased levels." (PMID 38494863, 2024). "Death receptors TRAIL‐R1, TRAIL‐R2 and Fas as well as immunogenic cell death marker calreticulin were upregulated in cell lines post infection." (PMID 38494863, 2024). "Nevertheless, all markers (Caspase 3/7, calreticulin and ATP) considered, apoptosis is involved in the death mechanisms post LOAd infection especially when LOAd expresses the TMZ‐CD40L." (PMID 38494863, 2024). "In terms of neurochemistry, the proportions of myenteric neurons expressing either CalB or CalR, which are putative excitatory neurons, remained unchanged following infection." (PMID 39141685, 2024).
infection (continued). "OBP-702 infection induced an increase in ATP release, upregulation of calreticulin expression on the surface of GC cells, and intracellular HMGB-1 expression." (PMID 38745748, 2024). "Two and three of these calreticulin genes were induced after SA treatment and Cmm infection, respectively, and two of them were commonly upregulated after both interventions." (PMID 38434116, 2023). "Genes belonging to the Calreticulin and Gal_lectin families were enriched in the cluster of genes downregulated during the infection." (PMID 35050051, 2022). "CAZymes (such as cellulase, pectate lyase, calreticulin and expansin) are important for breaking down the polysaccharides of plant cell walls to establish infection." (PMID 34011295, 2021). "The infection induced significant cell surface expression of calreticulin at 6 h compared to mock treated cells p = 0.0032." (PMID 32225009, 2020). "For example, proteomic analysis of PMeV-infected papaya identified a total of 486 reproducible spots, among which calreticulin and the proteasome subunits 20S and RPT5a were upregulated during infection." (PMID 31170911, 2019). "When we infected RAW267.4 macrophages, the Mpt64 signal in Mtb-infected macrophages colocalized with calreticulin, confirming the subcellular localization of Mpt64 secreted during infection." (PMID 31167949, 2019). "When infection occurs, the exposed collagenous tail of SP-D adheres to the calreticulin/CD91 receptor complex and initiates a pro-inflammatory response by stimulating p38 MAPK phyosphorylation and NF-κB activation." (PMID 30337682, 2018). "Infection of N. benthamiana plants with potato virus X (PVX) induces a number of genes associated with the UPR including BIP, PDI, calreticulin (CRT) and calmodulin (CAM)." (PMID 28360918, 2017). "ER chaperones calnexin and calreticulin are markedly increased 16 hours post-infection (hpi) and protein disulfide isomerase (PDI) at later infection time points (48 hpi)." (PMID 28841179, 2017). "All these interactions enhance cellular infection using specific parasite surface molecules such as calreticulin (TcCRT), Tc45 mucin, and Tc85." (PMID 26752404, 2016). "In accordance, quantification analysis showed that HCV infection increased the colocalization of hCKα with CALR compared to that with mock infection." (PMID 27489281, 2016). "In this work, we assessed the effect of recombinant T. solium calreticulin (rTsCRT) on the cytokine, humoral and cellular responses upon experimental infection in Syrian Golden hamsters (Mesocricetus auratus)." (PMID 25811778, 2015). "We show that M. incognita expressed the calreticulin gene (Mi-crt) in infected rice roots and that several rice defense genes expression are down-regulated at an early stage of infection when the nematode starts feeding from root cells." (PMID 26224554, 2014). "Next, we investigated a potential colocalization of both vGPCRs during infection with calreticulin, a marker for the endoplasmic reticulum (ER)." (PMID 24517969, 2014). "Meloidogyne incognita expressed the immune suppressor calreticulin gene (Mi-crt) in rice roots all along its infection cycle." (PMID 26224554, 2014). "During infection, T. cruzi calreticulin (TcCRT) translocates from the endoplasmic reticulum to the area of flagellum emergence." (PMID 23991234, 2013). "Herein we show that T. cruzi calreticulin (TcCRT), a multifunctional protein, exteriorized by the parasite, mediates infection of human placenta, since it binds human complement component C1, a “danger signal” detector." (PMID 23991234, 2013). "Infective trypomastigotes use Tc85 to interact with laminin, p45 mucin to interact with LAMC1 through galectin-3 (LGALS3), a human lectin, and calreticulin (TcCRT) to interact with TSB1 to enhance cellular infection." (PMID 23133440, 2012).
infection (continued). "By 4 hours post-infection, around 35% of the bacteria co-localized with calreticulin in caspase-7−/− macrophages, whereas less than 5% bacteria associated with the ER marker in B6 macrophages." (PMID 19343209, 2009). "Moreover, intranasal administration of exogenous calreticulin significantly alleviated infection-induced pathological injury to the respiratory system and effectively decreased bacterial loads in infected tissues." (PMID 40723838, 2025). "In addition, after 12 hours of infection at varying MOIs, CALR mRNA levels in the MOI 50 group were significantly higher than in the other groups, while levels in the MOI 100 and MOI 200 groups were significantly lower than in the control group." (PMID 40019270, 2025). "Given smooth muscle hypertrophy occurred in both primary and secondary infection, the observed alterations in CalB+/CalR+ neurons may play a role in the faster transit time observed following secondary infection." (PMID 39141685, 2024). "Interestingly, in infected wild-type cells, Herpud1, Sel1L and calreticulin underwent rapid degradation following infection in wild-type and rUbe2g2WT cells, which was blocked in both the Ube2g2−/− and rUbe2g2C89K cells with increase in synthesis over time." (PMID 37164963, 2023). "Similarly, PMVEC expressing CALR-shRNA showed a higher rate of infection compared to their parental control cells." (PMID 38067122, 2023). "In addition, tomato plants expressing dsRNA to R. similis calreticulin were reported to show resistance to infection by the nematode." (PMID 37569502, 2023). "Given the marked necrotic fields in the liver sections from Gal-3 KO mice and the ability of MCMV to induce necroptosis, we examined markers of necroptotic death, HMGB1 in liver tissue homogenates and membrane expression of calreticulin on hepatocytes, 36 h after infection." (PMID 30800112, 2019). "If this is correct, it may be worth testing whether calreticulin injections during a bacterial infection help clear the infection by (i) opsonizing the bacteria, and (ii) enhancing phagocytosis and presentation of antigens from the bacteria." (PMID 31781126, 2019). "To test whether secreted Mpt64 localizes to the ER during infection, we assessed its colocalization with calreticulin in RAW267.4 cells using confocal immunofluorescence microscopy." (PMID 31167949, 2019). "Indeed, MV-Edm infection promoted membrane translocation of calreticulin, a critical molecule in activating dendritic cells." (PMID 28701757, 2017). "Calreticulin upregulation could potentially be a consequence of mitochondrial stress signalling during infection." (PMID 27724938, 2016). "In contrast, BCVs from macrophages infected with the mutant strains mCherry-ΔabcBA or mCherry-ΔvirB2 had a very low percentage of colocalization with calreticulin over course of infection, which coincided with the low percentage of macrophages containing intracellular bacteria (~5%; p<0.0001)." (PMID 26366863, 2015). "TSP1 promotes infection of Trypanosoma cruzi by binding to calreticulin." (PMID 23144964, 2012). "The abundance of calreticulin transcript in Ar. subalbatus responding to B. malayi infection showed no detectable change at 1, 3, 6, and 12 hours, but the transcript showed a detectable decrease in relative abundance at 24 and 48 hours post infection." (PMID 18088420, 2007). "Furthermore, we observed that SCh infection induces translocation of calreticulin to cell membrane." (PMID 28770174, 2017). "Immunization experiments combining AP with cathepsin X, calreticulin with SP, two different DNases II, or DNase II with CTR resulted in higher protection against infection compared to single-protein immunization." (PMID 40988998, 2025). "Infection, virus replication, and SS cell growth inhibition correlated with induction of stress and DAMP marker expression, including calreticulin and HMGB-1." (PMID 41235176, 2025).